CAMSAP1 (calmodulin regulated spectrin associated protein 1)
Description:
Key microtubule-organizing protein that specifically binds the minus-end of non-centrosomal microtubules and regulates their dynamics and organization. Specifically recognizes growing microtubule minus-ends and stabilizes microtubules. Acts on free microtubule minus-ends that are not capped by microtubule-nucleating proteins or other factors and protects microtubule minus-ends from depolymerization. In contrast to CAMSAP2 and CAMSAP3, tracks along the growing tips of minus-end microtubules without significantly affecting the polymerization rate: binds at the very tip of the microtubules minus-end and acts as a minus-end tracking protein (-TIP) that dissociates from microtubules after allowing tubulin incorporation. Through interaction with spectrin may regulate neurite outgrowth.
Synonyms: FLJ31228; DKFZp434F195; CDCBM12
Tractability: Small molecule: a structure with a bound ligand is known. PROTAC: ubiquitination databases record sites on it; its protein half-life has been measured.
Gene: Protein-coding gene on chromosome 9 (135,808,487 to 135,907,546, reverse strand). Ensembl gene ENSG00000130559.
Subcellular location: Cytoplasm, cytoskeleton
Subcellular location (Human Protein Atlas): Cytosol; Mitotic spindle
Gene Ontology:
Molecular function: microtubule binding; microtubule minus-end binding; spectrin binding; calmodulin binding
Biological process: microtubule cytoskeleton organization; neuron projection development; regulation of microtubule polymerization
Cellular component: cytosol; microtubule; microtubule minus-end; mitotic spindle; cytoskeleton
Genetic constraint (gnomAD): Loss-of-function variants: 53 observed, 122.48 expected, observed/expected ratio (o/e) 0.43, 90% interval 0.35 to 0.54. The upper end of that interval is the gene's LOEUF score, 0.54, which puts it in group 2 of 6, group 1 being the genes least tolerant of losing a copy. Missense variants: 1,931 observed, 2,055 expected, observed/expected ratio (o/e) 0.94, 90% interval 0.9 to 0.98. Synonymous variants: 932 observed, 846.32 expected, observed/expected ratio (o/e) 1.1, 90% interval 1.04 to 1.16.
Homologues: Orthologues: chimpanzee CAMSAP1 (99% identical), macaque CAMSAP1 (97% identical), rat Camsap1 (85% identical), mouse Camsap1 (84% identical), dog CAMSAP1 (84% identical), guinea pig CAMSAP1 (82% identical), pig CAMSAP1 (77% identical), tropical clawed frog camsap1 (67% identical), zebrafish camsap1b (56% identical), zebrafish camsap1a (48% identical), Drosophila melanogaster Patronin (23% identical), Caenorhabditis elegans ptrn-1 (18% identical). Paralogues in human: CAMSAP2 (39% identical), CAMSAP3 (28% identical).
Diseases named in the same sentence as CAMSAP1 in open-access papers:
CAMSAP1 is named in the same sentence as 36 diseases in open-access papers, as found by Europe PMC text mining. Sharing a sentence is not in itself a finding about the gene and the disease. The quoted sentences say what the papers report.
small cell lung carcinoma (3 papers, 2021 to 2025). Small cell lung cancer (SCLC) is a highly aggressive malignant neoplasm, accounting for 10-15% of lung cancer cases, characterized byrapid growth, and early metastasis. "Gene expression analysis obtained from tumor specimens demonstrated that CAMSAP1 mutations, mainly occurring in its CH and CKK domains, significantly correlated with better prognoses in small cell lung cancer, whereas CAMSAP1 expression was not relevant to overall survival rates." (PMID 36188577, 2022).
COVID-19 (2 papers, 2021 to 2023). A disease caused by infection with severe acute respiratory syndrome coronavirus 2. "Serum levels of hsa-miR-29a-3p, hsa-miR-31-3p and hsa-miR-126-3p are reduced with increased severity of COVID-19, and the relative expression levels of COL5A3, ZMYM5 and CAMSAP1 are also increased with increased severity of COVID-19." (PMID 37661862, 2023). "Conversely, in COVID-19 patients who respond to treatment (f), the relative expression of ZMYM5, COL5A3, and CAMSAP1 was significantly decreased and the relative expression of DICER1 was significantly increased during hospitalization." (PMID 34256840, 2021). "In COVID-19 patients who did not respond to treatment (e), the relative expression of ZMYM5, COL5A3, and CAMSAP1 was significantly increased and the relative expression of DICER1 was significantly decreased during hospitalization." (PMID 34256840, 2021).
nasopharyngeal carcinoma (2 papers, 2024 to 2025). A carcinoma arising from the nasopharyngeal epithelium. "For example, c-Myc, in combination with splicing factor 10 (SRSF10), can promote the transcription and back-splicing of CAMSAP1 precursor mRNA, leading to the proliferation and metastasis of nasopharyngeal carcinoma." (PMID 38926764, 2024).
hypertrophy (1 paper, 2025). Hypertrophy is the increase in the volume of an organ or tissue due to the enlargement of its component cells. "Rare variants in CAMSAP1 (score 7) were found in 8 participants with severely increased LVWT but not in participants with milder hypertrophy (p < 0.001)." (PMID 40791945, 2025).
laryngeal squamous cell carcinoma (1 paper, 2022). A squamous cell carcinoma that arises from the larynx. "As for the CAMSAP1 regulatory miRNA, it has been previously reported that the downregulation of CAMSAP1 in primary human osteoblasts and laryngeal squamous cell carcinoma is caused by upregulation of miR-126." (PMID 36212130, 2022).
Lissencephaly (1 paper, 2022). A spectrum of malformations of cortical development caused by insufficient neuronal migration that subsumes the terms agyria, pachygyria and subcortical band heterotopia. "High embryonic expression in the developing face tissues and cortex from E10.5–18.5 would be consistent with craniofacial abnormalities and CNS malformations such as microcephaly and lissencephaly, which we observe in individuals with CAMSAP1-related neuronal migration disorder." (PMID 36283405, 2022).
liver cancer (1 paper, 2020). An epithelial or non-epithelial malignant neoplasm that arises from the liver. "Immunohistochemistry (IHC) tissue microarray data from Human Protein Atlas program database revealed high or medium CAMSAP2 staining intensity in 10 out of 12 liver cancer samples, whereas only 3 out of 12 cases showed medium staining of CAMSAP1 and CAMSAP3." (PMID 32206120, 2020).
male infertility (1 paper, 2024). The inability of the male to effect fertilization of an ovum after a specified period of unprotected intercourse. "Previous studies have shown that loss of Camsap1 results in mice displaying abnormalities in sperm morphology, reduced sperm count, decreased sperm motility, ultimately leading to male infertility." (PMID 38799061, 2024). "Meanwhile, studies have found that knockout of Camsap1 results in male infertility." (PMID 38799061, 2024).
neuronal migration disorder (1 paper, 2022). "Using exome sequencing on samples from five unrelated families, we show that bi-allelic CAMSAP1 loss-of-function variants cause a clinically recognizable, syndromic neuronal migration disorder." (PMID 36283405, 2022). "There are, however, distinct clinical, neuroradiological, and pathophysiological features only associated with the CAMSAP1-related neuronal migration disorder." (PMID 36283405, 2022). "Here, we define bi-allelic CAMSAP1 (MIM: 613774) variants as a cause of a clinically and radiologically distinct syndromic neuronal migration disorder." (PMID 36283405, 2022). "Our findings thus implicate Camsap1 in these neuronal migration processes, potentially explaining the clinical findings in affected individuals with the CAMSAP1-related neuronal migration disorder." (PMID 36283405, 2022). "Conversely, hypogenesis of the corpus callosum is typically seen in the tubulinopathies, whereas agenesis is very rarely described but was universally seen in individuals affected by the CAMSAP1-related neuronal migration disorder." (PMID 36283405, 2022). "Notable neuroradiological differences between the CAMSAP1-related neuronal migration disorder and the tubulinopathies involve the cerebellar and corpus callosum phenotypes." (PMID 36283405, 2022). "At the milder end of the tubulinopathies spectrum, cerebellar hypoplasia with an abnormal folia pattern may be the only abnormality present, while folia patterning is apparently preserved in the CAMSAP1-related neuronal migration disorder." (PMID 36283405, 2022). "This phenotype is analogous to the early and severe forms of epilepsy invariably observed in individuals with the CAMSAP1-related neuronal migration disorder, with the lack of perinatal mortality observed in humans potentially explained by the efficacy of pharmacological anti-epileptic therapies." (PMID 36283405, 2022).
pancreatic cancers (1 paper, 2022). "Next, we used the Oncomine database to verify CAMSAP1 expression and found that the expression was significantly increased in colorectal, gastric, kidney, liver, and pancreatic cancers." (PMID 36212130, 2022).
tumor (6 papers, 2021 to 2025). "CAMSAP1 mutations serve as a predictive indicator in cancer patients triggering anti-tumor immunity, mediate tumor cell apoptosis, improve prognosis, and improve sensitivity to platinum-based chemotherapy." (PMID 40557274, 2025). "This study conducted pan-cancer analyses of CAMSAP1 expression, and demonstrated that CAMSAP1 upregulation was associated with advanced tumor and unfavorable prognosis in LIHC." (PMID 36212130, 2022). "Analyses of the mechanism showed that CAMSAP1 mutation can activate anti-tumor immunity, mediate apoptosis of tumor cells and inhibit EMT." (PMID 35087829, 2021). "The inverse correlation between miR-126-3p and Camsap1 expression, as well as circulating tumor cell counts, suggests a mechanistic role in modulating the tumor microenvironment." (PMID 39941323, 2025). "Collectively, these results demonstrated that in addition to immune cell infiltration, tumor immune escape mediated by immune checkpoints and CAFs is also involved in CAMSAP1-mediated LIHC progression and ICB treatment is effective in these patients." (PMID 36212130, 2022). "The results were consistent, also showing that anti-tumor immunity, platinum-mediated apoptosis and cell activity pathways were significantly up-regulated in CAMSAP1-MT groups in the two cohorts." (PMID 35087829, 2021). "Our work further indicated that CAMSAP1 was positively correlated with the major types of immune cells, suggesting that tumor immune infiltration may exert an antitumor effect in CAMSAP1-mediated LIHC." (PMID 36212130, 2022). "Results showed that CAMSAP1 expression was significantly correlated with the weight (p = 0.04), T stage (2.8e-04), pathologic stage (3.4e-04), histologic grade (8e-03), tumor status (6e-03), and residual tumor (0.01)." (PMID 36212130, 2022). "In the CAMSAP1-MT group, GSVA scores of anti-tumor immunity, platinum-mediated apoptosis, and cell activity pathways were significantly higher than those in the CAMSAP1-WT group, and patients with high GSVA scores showed better prognosis than those with low GSVA scores." (PMID 35087829, 2021). "Studies have shown that CAMSAP1 dysfunction can lead to abnormal neuronal polarity and impaired migration, a mechanism that may be hijacked in tumor metastasis: −TIPs remodel the spatial conformation of the cytoskeletal network by modulating microtubule dynamic stability." (PMID 41464116, 2025). "The functions of this family members in tumors show significant heterogeneity, with CAMSAP1 and CAMSAP2 mainly exerting pro-tumorigenic effects, while CAMSAP3 exhibits tumor suppressor properties." (PMID 41464116, 2025). "However, the expression, diagnosis, survival, and correlation analyses of CAMSAP1 with tumor immune infiltration in LIHC have not been comprehensively evaluated." (PMID 36212130, 2022).
cancer (3 papers, 2015 to 2022). A tumor composed of atypical neoplastic, often pleomorphic cells that invade other tissues. "In this study, we conducted comprehensive pan-cancer analyses of CAMSAP1 and demonstrated that CAMSAP1 expression is associated with genetic alteration and DNA methylation." (PMID 36212130, 2022). "We performed systematical analyses of CAMSAP1 and demonstrated that differential expression of CAMSAP1 is associated with genetic alteration and DNA methylation, and serves as a potential diagnostic and prognostic biomarker in some cancers, especially LIHC." (PMID 36212130, 2022). "CNAs are the genetic variation most associated with CAMSAP1 expression, and most of the 22 cancers showed positive correlation with its expression, especially ACC (r = 0.64, p = 4.03e-10), OV (r = 0.61, p = 9.43e-32), and BLCA (r = 0.53, p = 6.56e-31)." (PMID 36212130, 2022). "To confirm the suggestion, we evaluated the diagnostic value and survival effect of CAMSAP1 in cancers." (PMID 36212130, 2022). "Other genes we found to be altered by miR-126-3p expression include PIK3R2 and CAMSAP1, which have also been implicated in cancer biology." (PMID 26244545, 2015). "In recent years, as non-centrosomal MT minus binding proteins, members of the Calmodulin-regulated spectrin-associated protein (CAMSAP) family, including CAMSAP1, CAMSAP2, and CAMSAP3, have attracted increasing attention for their role in cancers." (PMID 36212130, 2022). "CAMSAP1 genetic variation included amino acid mutation and CNAs, among these 32 cancer types (COAD and READ are merged into COADREAD), 25 of them contained CAMSAP1 mutation, and 22 had CNAs." (PMID 36212130, 2022). "In addition to genetic alteration and DNA methylation regulation in pan-cancer, we introduced ncRNAs well-known for their role in regulating gene expression to further explore the regulatory mechanism of CAMSAP1 overexpression in LIHC." (PMID 36212130, 2022). "Taken together, these results suggest that CAMSAP1 expression may play an important regulatory role in the carcinogenesis of at least 10 cancer types." (PMID 36212130, 2022). "Therefore, we first used cBioPortal (TCGA, Pan-Cancer Atlas) to study the relationship between CAMSAP1 expression and genetic variation." (PMID 36212130, 2022). "Firstly, the ENCORI portal predicted upstream miRNAs that could bind to CAMSAP1 in several cancers and a total of 74 miRNAs were found in pan-cancer." (PMID 36212130, 2022).
neurodevelopmental disorder (1 paper, 2022). A behavioral and cognitive disorder with onset during the developmental period that involves impaired or aberrant development of intellectual, motor, or social functions. "Together our findings confirm a fundamental role of CAMSAP1 in neuronal migration and brain development and define bi-allelic variants as a cause of a clinically distinct neurodevelopmental disorder in humans and mice." (PMID 36283405, 2022).
CAMSAP1 also shares sentences with these, for which no sentence is quoted: hepatocellular carcinoma (2 papers); cervical cancer (1); cervical squamous cell carcinoma (1); cholangiocarcinoma (1); colon adenocarcinoma (1); colorectal carcinoma (1); diffuse large B-cell lymphoma (1); endocervical adenocarcinoma (1); esophageal carcinoma (1); glioblastoma multiforme (1); head and neck squamous cell carcinoma (1); low grade glioma (1); lung squamous cell carcinoma (1); Pan (1); pancreatic adenocarcinoma (1); paraganglioma (1); pheochromocytoma and (1); prostate carcinoma (1); rectum adenocarcinoma (1); thymoma (1); thyroid cancer (1); tubulinopathies (1); viral infection (1).